MMP3 (matrix metallopeptidase 3)
Diseases named in the same sentence as MMP3 in open-access papers (continued):
Sharing a sentence is not in itself a finding about the gene and the disease.
glaucoma (22 papers, 2009 to 2025). Increased pressure in the eyeball due to obstruction of the outflow of aqueous humor. "We found that the MMP3 rs3025058 TT genotype was associated with more advanced glaucoma and a higher C/D ratio in the additive and dominant models, while the MMP9 rs520544 CC genotype was marginally associated with a thicker CCT." (PMID 39769228, 2024). "Among those, six genes (Lyz2, Apoe, Crybb2, Pvalb, Cryab, Mmp3) were found to be associated with glaucoma when compared with the reference glaucoma genes." (PMID 37377596, 2023). "Presently, TDRD7, CYP1B1, GJA1, IL1B, MMP1, and MMP3 have been considered as a causative gene for glaucoma." (PMID 33299458, 2020). "In terms of the glaucoma phenotype, we found that the MMP3 rs3025058 TT genotype was associated with more advanced glaucoma and a higher C/D ratio in the additive and dominant models, while the MMP9 rs520544 CC genotype was marginally associated with a thicker CCT." (PMID 39769228, 2024). "Adeno-associated virus (AAV) vectors deliver MMP3 for the treatment of glaucoma." (PMID 37075118, 2023). "Therefore, the lowered MMP-3 expression and activity may cause the progression of glaucoma by the impediment of aqueous humor outflow." (PMID 35457074, 2022). "AAV9-mediated expression of matrix metalloproteinase 3 (MMP3) increased fluid outflow in two glaucoma models in mice and primates." (PMID 40002778, 2025). "Only carriers of the MMP3 rs3025058 TT genotype had a significantly higher risk of OHT, more advanced glaucoma, and a higher C/D ratio in the additive and dominant models." (PMID 39769228, 2024). "Our findings revealed a significant decrease in the mRNA levels of SA1009 and MMP3 in the glaucoma model group compared to the normal group, while SERPINA3, IL1RN, and LCN2 expression increased." (PMID 39125762, 2024). "In two distinct mouse models of glaucoma, we show that intracameral delivery of MMP-3 via AAV9 is efficacious at increasing outflow and decreasing IOP." (PMID 37075118, 2023). "It is also important to note that MMP-3 activity was found to be lower in the aqueous humor in patients with glaucoma compared to age-matched ocular normotensive controls." (PMID 35457074, 2022). "Our results confirm elevated MMP-2 and MMP-3 levels in glaucoma AqH." (PMID 41154592, 2025). "A recent study used MMP3 as a gene therapy option for glaucoma treatment." (PMID 39125762, 2024). "TIMPs were increased in the plasma of untreated children with JIA, have been associated with levels of matrix metalloproteinase (MMP)-1, MMP-3, and TIMP1 in paired serum and synovial fluid also in those with JIA, and were found in AqH of patients with glaucoma." (PMID 30327966, 2018). "Strikingly, the staining intensity of MMP1 and MMP3 in the outflow pathway of exfoliating glaucoma, a type of secondary glaucoma characterized by the extracellular accumulation of non-internalized exfoliating material in the angle chamber, was significantly diminished compared to POAG." (PMID 22529935, 2012). "The distribution of genotypes and alleles in MMP1 and MMP3 polymorphisms was not significantly different between cases with exfoliation syndrome, with or without glaucoma, and controls." (PMID 20038976, 2009). "Interestingly, MMP3 was recently shown to be an appealing target for treating glaucoma." (PMID 40969146, 2025). "Luminex analysis of AqH samples revealed significantly elevated levels of MMP-2, MMP-3, ET-1, sEMMPRIN, ZAG, sLOX-1, follistatin, cortisol, endostatin, sTIE-2, and PDGF-BB in glaucoma participants (adjusted p < 0.05)." (PMID 41154592, 2025). "Our study identified and validated six neuroinflammation-related hub genes in glaucoma (SERPINA3, LCN2, MMP3, S100A9, IL1RN, and HP)." (PMID 39125762, 2024). "For example, AAV-delivered matrix metalloproteinase-3 (MMP-3)-mediated gene therapy has been shown to increase outflow and reduce IOP in a variety of glaucoma models." (PMID 39201561, 2024).
glaucoma (continued). "MMP-3 and MMP-9 are two members of this enzyme group that have been shown to be particularly affected in patients with glaucoma." (PMID 37233995, 2023). "MMP-3 and MMP-9 are 2 members of this enzyme group, and their presence has been found to be particularly influenced by the presence of glaucoma." (PMID 37233995, 2023). "The level of MMP-3 was significantly lower in PACG compared to in POAG, and comparable to the non-glaucoma controls." (PMID 24655889, 2014). "Furthermore, elevated intraocular levels of MMP-3, ZAG, and APN were identified as biomarkers for impaired perfusion in glaucoma." (PMID 41154592, 2025). "Here, we show that adeno-associated virus 9 (AAV9)–mediated expression of matrix metalloproteinase-3 (MMP-3) can increase outflow in two murine models of glaucoma and in nonhuman primates." (PMID 37075118, 2023). "MMP2, MMP3, and TIMP1 were also detected in higher, but not significantly different, amounts in aqueous samples of primary open-angle glaucoma eyes." (PMID 41009516, 2025). "They found that MMP2, MMP3, TIMP1, and TIMP2 were detected at significantly higher concentrations in aqueous samples from eyes with pseudoexfoliation with and without glaucoma compared with cataractous eyes." (PMID 41009516, 2025). "We also found an increased expression of MMP-2, MMP-3, MMP-9, TGFβ-1, and TGFβ-3 in eyes with JIAU, independent of the presence of glaucoma." (PMID 29675026, 2018).
hepatocellular carcinoma (22 papers, 2011 to 2025). A malignant tumor that arises from hepatocytes. "The polymorphism of MMP-3 (genetic variants) is associated with poor prognosis in hepatocellular carcinoma and primary sclerosing cholangitis (PSC)." (PMID 35529854, 2022). "MMP-3 is a stromelysin that is expressed in a variety of cell types, including hepatocellular carcinoma cells and hepatic stellate cells." (PMID 35529854, 2022). "On the other hand, reports have shown that lower expression of miR-30a-3p is correlated with lower levels of MMP3 and vimentin as well as higher levels of E-cadherin in hepatocellular carcinoma cells." (PMID 31217934, 2019). "On the other hand, TH negatively regulated the mature miR-17 transcript expression to increase MMP3 expression in hepatocellular carcinoma (HCC)." (PMID 30360449, 2018). "Similar ROS-dependent Snail induction has been reported in hepatocellular carcinoma cells and in MMP-3/Rac1b signal cascade-mediated EMT of mouse mammary epithelial cells." (PMID 21448462, 2011). "MMP3 is known to manipulate cell phenotype and promote tumor invasion in hepatocellular carcinoma." (PMID 36553576, 2022). "Src and ERK have been reported to participate in the MMP3 expression in hepatoma and in osteoarthritis, we therefore tested whether GBP5 had influence on the activation of Src and ERK1/2." (PMID 33608513, 2021). "Regarding MMP-3 subcellular localization, MMP-3 has been found in the nucleus and might be involved in the transcriptional or apoptosis processes in some cells, such as hepatocellular carcinoma, chondrocytes, and myofibroblast." (PMID 37513440, 2023). "The mRNA levels of both MMP-2 and MMP-14 in human hepatocellular carcinoma (HCC) cell SMMC-7721 were up-regulated by Cu2+ in a concentration dependent manner, whereas the mRNA levels for other tested MMPs (MMP-1, MMP-3 and MMP-9) were not changed when treated with up to 40 μM Cu2+." (PMID 28881637, 2017).
synovitis (22 papers, 2006 to 2025). Inflammation of a synovial membrane. "Multiple regression analysis showed that serum MMP-3 concentration was associated with mild effusion-synovitis detected on MRI." (PMID 32704147, 2020). "Serum MMP-3 concentration was associated with effusion-synovitis volume β = 0.60, p < 0.001)." (PMID 32704147, 2020). "Serum MMP-3 was higher in RA patients with high-grade synovitis than patients with low-grade synovitis and significantly correlated with the synovitis score and the activation of the synovial stroma subscore." (PMID 40725063, 2025). "Our study results revealed an intrinsic deficiency of CD8+ Tregs in patients with EORA, which leaves synovitis unchecked with excessive MMP-3 release." (PMID 36983342, 2023). "A recent study revealed that synovitis is one of the key factors in identifying early OA which was confirmed through the analysis of serum matrix metalloproteinase-3 (MMP-3) concentration, effusion-synovitis volume and synovial score." (PMID 36361805, 2022). "The importance of MMP-3 in RA pathogenesis is reflected in its level, in the synovial fluid in synovitis." (PMID 35967336, 2022). "Serum MMP-3 concentration and effusion-synovitis volume were higher in patients with EKOA (p = 0.025 and p = 0.001, respectively)." (PMID 32704147, 2020). "The serum MMP-3 concentration, effusion-synovitis volume, and synovial score are valuable metrics for elucidating the characteristics of EKOA." (PMID 32704147, 2020). "Third, our data showed that serum MMP-3 concentrations significantly correlated with effusion-synovitis volume, but the correlation was relatively weak." (PMID 32704147, 2020). "Our previous studies showed that serum MMP-3 level in RA was increased and positively correlated with disease activity, histological synovitis and synovial MMP-3 expression." (PMID 26467222, 2015). "Serum MMP-3 was higher in RA patients with high grade synovitis than that of low grade synovitis and significantly correlated with synovitis score and activation of synovial stroma subscore (all P < 0.05)." (PMID 25147433, 2014). "Here, we explored the correlation of serum MMP-3 or synovial MMP-3 expression with histological synovitis and the significance for the diagnosis of RA." (PMID 25147433, 2014). "Our results showed that synovial MMP-3 was elevated in RA synovium and positively correlated with synovitis assessed by comprehensive histological analysis including Krenn's synovitis score and inflammatory cells by immunohistochemistry." (PMID 25147433, 2014). "ROC curve analysis showed that the tradeoff value of serum MMP-3 for distinguishing high grade synovitis in RA was 190 ng/mL with sensitivity 93% and specificity 49%." (PMID 25147433, 2014). "Immuno-histochemistry in peripheral synovitis of spondarthritis patients also shows high levels of MMP-3, with downregulation after biological treatment." (PMID 24078814, 2013). "The correlation between MMP-3 and the number of positive regions and the total score in untreated pSpA may be reflective of synovitis in peripheral articular." (PMID 36792786, 2023). "Therefore, OA progresses in a vicious cycle in which MMP-3 increases synovitis, and synovitis enhances MMP-3 production." (PMID 38066785, 2023). "In the second search, 71 papers on MMP3 and synovitis were collected in patients with RA." (PMID 35212285, 2022). "In this study, we performed histological synovitis analysis to investigate the potential of MMP-3 as a serological biomarker of synovitis, which is an enzyme synthesized in the synovium, secreted into synovial fluids in joint cavities, and then gains access into peripheral circulation." (PMID 25147433, 2014). "Further studies are required to investigate whether serum active MMP-3 is more sensitive and reliable serological biomarker of synovitis than total MMP-3." (PMID 25147433, 2014).
synovitis (continued). "Compared to the device-depended imaging assessment and invasive synovial biopsy, serum MMP-3 is more suitable for repeated assessments of synovitis and it may be an alternative noninvasive biomarker of synovitis for clinical practice." (PMID 25147433, 2014). "Studies have shown that MMP-3 is not directly involved in the progression of synovitis, but the products of decomposing cartilage matrix, such as cartilage oligomeric matrix protein and damage-associated molecule patterns, can recruit inflammatory cells, leading to synovitis." (PMID 34276395, 2021). "Effusion-synovitis volume negatively correlated with all KOOS subscales and positively correlated with serum MMP-3 concentration." (PMID 32704147, 2020). "We also found that correlation between MMP-3 and the US7 synovitis score was much stronger than for tendon sheath synovitis and bone destruction scores." (PMID 29141665, 2017). "According to the tradeoff value of the percentage of lining MMP3+ cells for distinguishing high grade and low grade synovitis, RA patients were divided into high synovial MMP-3 expression (>44%) and low synovial MMP-3 expression groups (≤44%)." (PMID 25147433, 2014). "Serum MMP-3 was significantly correlated with synovial MMP-3 and Krenn's synovitis score and had the ability to distinguish high grade from low grade synovitis in RA." (PMID 25147433, 2014). "MMP-3 is not directly involved in the progression of synovitis, but the products of cartilage matrix decomposition, such as cartilage oligomeric matrix proteins and damage-related molecular patterns, can recruit inflammatory cells and lead to synovitis." (PMID 35967336, 2022). "In sum, this study indicated that WB had obvious inhibitory effects on synovitis of CIA rats, and the mechanisms of which may be involved in downregulating the expression levels of several key proteins including MMP3, MMP19, LBP, IRAK4, and ARPC5." (PMID 34708132, 2021). "On the contrary, there was a significantly negative correlation between the expression level of MMP3 and synovitis score." (PMID 33507995, 2021). "In this study, we found significant correlations between synovial MMP-3 and serum MMP-3, CRP, or ESR and significant correlation between serum MMP-3 and synovitis score with high sensitivity of serum MMP-3 in diagnosing high grade or low grade synovitis by ROC curve." (PMID 25147433, 2014). "Immunohistochemical studies have found that, particularly in early OA, this synovitis has a mononuclear cell infiltrate, with considerable production of proinflammatory cytokines like TNF-α and IL-1β and destructive enzymes like MMP-1 and MMP-3." (PMID 17177994, 2006). "Both the synovial score and the effusion-synovitis volume in the EKOA group were significantly higher than those in the normal group (p = 0.003 and p = 0.001, respectively).There was a weak positive correlation between serum MMP-3 concentration and effusion-synovitis volume (r = 0.176, p = 0.003)." (PMID 32704147, 2020). "Using Krenn's synovitis score, we found that synovial MMP-3 was significantly correlated with hyperplasia of lining layer subscore and activation of synovial stroma subscore, and activation of synovial stroma was incorporated in the multiple linear regression model for synovial MMP-3." (PMID 25147433, 2014).
myocardial infarction (21 papers, 2008 to 2025). Gross necrosis of the myocardium, as a result of interruption of the blood supply to the area, as in coronary thrombosis. "Caspase-1 deficient mice with myocardial infarction have displayed a significant reduction in mortality and reduced cardiomyocyte pro-apoptosis, decreased MMP-3 activity, and IL-18 production." (PMID 41231039, 2025). "In univariate analysis, age ≥ 62 years, myocardial infarction in medical history, and log MMP-3 ≥ 1.12 were associated with the highest increases in CA risk (OR = 4.7, OR = 4.47, and OR = 4.45, respectively)." (PMID 35011813, 2021). "The chromosome 6p22 region we found linked to MMP3 levels is linked to sarcoidosis, schizophrenia, reading ability, pulse pressure, and early onset myocardial infarction." (PMID 23936524, 2013). "Matrix metalloproteinase (MMP3) plasma concentrations are linked to increased risk of plaque rupture and, thus, to myocardial infarction." (PMID 23936524, 2013). "Contrarily, the 6A allele has been associated with higher MMP-3 levels in patients with coronary heart disease and myocardial infarction, indicating the intricate relationship between gene polymorphisms,disease susceptibility, and the potential modulatory role of local and systemic conditions." (PMID 39712510, 2024). "In all cases of myocardial infarction, median serum levels of MMP-3 (stromelysin), MMP-9, PAPP-A, TIMP-1 were 14.11 pg/ml, 58.6 pg/ml, 1.3 μg/ml, 93.85 pg/ml respectively whereas the mean serum MCP-1 was 650.57 ± 625.42 pg/ml." (PMID 39351476, 2024). "It is therefore possible that the in vivo upregulation of Mmp3 by rosiglitazone will promote plaque rupture, leading to increased rates of myocardial infarction, as well as increasing tissue remodeling after ischemia." (PMID 18648539, 2008). "Mmp3 is typically expressed by macrophages within the atherosclerotic plaques found in coronary artery disease, and has been shown to promote plaque rupture, myocardial infarction and aneurysm." (PMID 18648539, 2008). "Colchicine reduced mRNA and protein expression of MMP2 in vitro, mitigated mRNA expression of MMP-3, MMP-9, and MMP-10 in aortas of mice and abolished the relative mRNA expression of MMP-9 in infarct area of myocardium after myocardial infarction in mice." (PMID 38001470, 2023). "Meanwhile, recent studies showed that a variety of MMPs increase in the myocardium after myocardial infarction, including MMP-1, MMP-2, MMP-3, MMP-7, MMP-9, MMP-11, and so on." (PMID 25237357, 2014). "Of the chosen polymorphisms, two (Leu125Val PECAM1 and A1/A2 FVII) are related to myocardial infarction and two (C677T MTHFR and 5A/6A MMP3) to advanced stenosis in arterial vessels (> 75%)." (PMID 23274712, 2013).